AKT2 (AKT serine/threonine kinase 2)
Diseases named in the same sentence as AKT2 in open-access papers (continued):
Sharing a sentence is not in itself a finding about the gene and the disease.
pancreatic cancer (34 papers, 2005 to 2025). "Furthermore, AKT2 overexpression was associated with the resistance to erlotinib in pancreatic cancer cell lines, indicating that AKT2 is involved in the occurrence of drug resistance." (PMID 35013144, 2022). "AKT2 amplification is frequently detected in various tumors, including ovarian, breast, colorectal, and pancreatic cancers, and is positively correlated with increased invasion and poor prognosis." (PMID 40041495, 2025). "In mouse pancreatic cancer, dual inhibition of K-Ras and Akt2 inhibits cell proliferation and tumor growth." (PMID 38291468, 2024). "AKT1 appears to contribute more to pancreatic cancer growth whereas AKT2 and AKT3 contribute more to phosphorylating downstream targets." (PMID 38920688, 2024). "In a pancreatic cancer xenograft model, blue LED inhibited tumor growth associated with reduced AKT2 levels." (PMID 39439950, 2024). "In this context, increased activation of AKT1 has been reported in both breast and colorectal cancer, whilst pancreatic cancers frequently have increased expression of AKT2." (PMID 36127435, 2022). "VAV1 inhibits the metastasis and therapy resistance by downregulating the Akt2 (AKT serine/threonine kinase 2) signaling pathway in pancreatic cancer." (PMID 34335756, 2021). "In pancreatic cancer, elevated AKT2 expression indicates shortened progression-free survival and overall survival." (PMID 32873299, 2020). "Other targets of MIR296 are the proto-oncogenes AKT2 in pancreatic cancer, PLK1 in non-small cell lung cancer, SP1 in cervical cancer and CDX1 in gastric cancer." (PMID 32582296, 2020). "In particular, both Akt1 and Akt2 are markedly activated in primary pancreatic tumors and tumor metastases, and Akt2 was positively correlated with resistance of PDAC to chemotherapy." (PMID 32993067, 2020). "AKT2 is an important regulator of pancreatic cancer development and, thus, an interesting link between miR-615-5p and PDAC prognosis." (PMID 25856297, 2015). "Significantly, cancer gene AKT2 was amplified in two pancreatic cancer patients, and cancer gene CDKN2C was homozygously deleted in other two cases." (PMID 25502777, 2014). "Akt2 overexpression and amplification have been described in breast, ovarian and pancreatic cancers." (PMID 15987444, 2005). "Importantly, AKT2 is a major downstream effector of phosphatidylinositol 3-kinase and considered to be a potential target for pancreatic cancer therapy." (PMID 25856297, 2015). "AKT2 is amplified in 10–20% of pancreatic cancers and activated in up to 60% of pancreatic tumors." (PMID 25856297, 2015). "Active AKT2 signaling promotes cell growth and resistance to chemotherapy in pancreatic cancer." (PMID 25856297, 2015). "And in the future, whether the drug Z-LLNIe-CHO could be used to treat the pancreatic cancer patients with AKT2 amplification should be studied." (PMID 25502777, 2014). "Our results further verified the amplification of AKT2 in pancreatic cancer." (PMID 25502777, 2014). "All these results suggested that amplification of AKT2 maybe develop into a biomarker to divide the pancreatic cancer patients into different subgroups for applying different therapy strategy." (PMID 25502777, 2014). "Indeed, AKT2 is amplified and overexpressed in pancreatic carcinomas and AKT2 antisense RNA can greatly diminish the tumorigenic phenotype of pancreatic cancer cells harboring amplified AKT2." (PMID 23874448, 2013). "Akt2 is amplified in some pancreatic cancers near this region." (PMID 24281169, 2010).
pancreatic cancer (continued). "Thus, miRNA-mediated inhibition of AKT2 might represent a useful therapeutic strategy in AKT2-amplified pancreatic cancer." (PMID 25856297, 2015). "RNAi simultaneously targeting AKT2 and K-ras could inhibite the pancreatic tumor growth." (PMID 25502777, 2014). "For example, 21 nt i-tRF-Gly interacts with hnRNPL and then prevents phosphorylation of hnRNPL by AKT2, thereby reducing the AKT2-hnRNAPL-DDX17 axis and attenuating the malignant phenotype in pancreatic cancer cells." (PMID 36360311, 2022). "Gene expression data from the cancer cell line encyclopedia (CCLE) assessing global Met expression along with its ligand, HGF, and other downstream kinases (MAPK1, AKT2, and AKT3) supported high Met expression in pancreatic cancer cell lines." (PMID 31903112, 2020). "We found that the accumulation of Vav1 inside the nucleus inversely correlates with Akt2 expression in both PDAC-derived cells and pancreatic tumor tissues." (PMID 32993067, 2020). "To further determine if there was any correlation between expression of AKT2 and miR-615-5p in PDAC patients, we performed immunohistochemical staining for AKT2 in 97 pairs of primary pancreatic tumor tissues and adjacent normal tissues." (PMID 25856297, 2015). "AKT2 and MCM7 were overexpressed, and CAMTA2 and PFN1 were underexpressed in pancreatic cancer tissues than in morphologically normal operative margin tissues." (PMID 25502777, 2014). "This is consistent with the observation that overexpression of constitutively active AKT2 not only failed to rescue Gli1 activity in pancreatic cancer cells lacking K-Ras, but also further decreased it, albeit not significantly." (PMID 23900341, 2013). "Genetic alterations in tumor suppressor genes found in lower frequency (<10%) in pancreatic cancer include STK11/LKB1, MKK4, TGFβ R1 (ALK 5, chromosome 9q), TGFβ R2 (chromosome 3p), ACVR1β (ALK 4, chromosome 12q), ACVR2 (chromosome 2q), FBXW7 (CDC4), EP300, BRCA2, ATM, and AKT2." (PMID 24624093, 2014). "However, the Mirk gene was among 16 genes within the consistently amplified 660 kb subregion of the 19q13 amplicon in pancreatic cancers, while the nearby gene Akt2 was not, making it very unlikely that the 19q13 amplicon was selected for because of Akt2." (PMID 24281169, 2010). "Our experiments excluded the involvement of miR-615, targeting Akt2 in MDA-MB-231 and pancreatic cancer cells, as it was not modified by Vav1 levels in this cell model." (PMID 35743776, 2022). "We previously reported that coamplification of AKT2 and ACTN4 did not necessarily accord for invasion of pancreatic cancer 5,11." (PMID 24574362, 2014).
colon carcinoma (30 papers, 2010 to 2025). "In colon cancer, it has been demonstrated that AKT2 can interact with and phosphorylate hexokinase 2 (HK2), the rate-limiting enzyme in glycolysis." (PMID 38396845, 2024). "In colon cancer, AKT2 overexpression affected radiation sensitivity and the DNA repair system, while AKT2 played a role in chemotherapy sensitivity and cancer cell survival in non-small cell lung cancer." (PMID 35887001, 2022). "To examine the cellular significance of the D44G/V45P/D46G triple mutation, we transfected the full-length Akt triple mutant into an Akt1/Akt2 knockout HCT116 human colon cancer cell line." (PMID 32744507, 2020). "Single knockdown of Akt1 and Akt2 leads to a decrease in Rad51 foci formation and significantly reduces Rad51 protein level in colon cancer cells." (PMID 32711558, 2020). "Taken together, our findings suggested that inhibition of AKT2 increases MEK1/2 phosphorylation in colon tumor cells." (PMID 32843616, 2020). "In this context, it is interesting that the results presented here for colon carcinoma HCT116 demonstrate a significantly stronger impact of Akt2 on homologous recombination repair of DSBs than that of Akt1." (PMID 31847370, 2019). "In agreement with this study, we demonstrate here significantly reduced Rad51 foci formation when AKT1 as well as AKT2 isoforms were downregulated alone or in combination with HCT116 colon cancer cells." (PMID 31847370, 2019). "The co-operativity between AKT2 and PTEN-deficiency was further demonstrated in colon cancer, where loss of PTEN function was required for enhanced liver metastasis of intrasplenically injected colorectal cancer cells overexpressing AKT2." (PMID 28082369, 2017). "Knockout of the rat Rac1 gene exon-3b or knockdown of endogenous Rac1b in human colon cancer HT29 cells downregulated only the AKT2/MCL1 pathway." (PMID 26918455, 2016). "Statistical analysis also revealed an inverse expression pattern between AKT2 and E-cadherin in human colon cancer tissues." (PMID 26434583, 2016). "Knockout of the rat Rac1 gene exon-3b or knockdown of endogenous Rac1b in HT29 human colon cancer cells downregulated only the AKT2/MCL1 pathway." (PMID 26918455, 2016). "This is consistent with recent findings in DLD-1 colon carcinoma cells in which AKT2 silencing resulted in increased FOXO3A activity leading to increased MXI1 RNA expression." (PMID 20604938, 2010). "Moreover, the AKT2 phosphorylation of hexokinase 2 has been demonstrated to enhance hexokinase activity and lactic acid production in colon cancer." (PMID 38396845, 2024). "In colon cancer, the expression of AKT2 can affect the DNA repair ability and radiosensitivity." (PMID 32873299, 2020). "Akt2 also plays a significant role in colon cancer metastasis." (PMID 26234648, 2015). "However, TS decrease the phosphorylation of AKT2 in colon cancer cells." (PMID 34543231, 2021). "We then hypothesized that AKT2 could also regulate EMT in colon cancer cells." (PMID 26434583, 2016). "HCT116 colon cancer cells with stable AKT-knock-out and siRNA-mediated AKT-knockdown phenotypes were used to investigate the role of Akt1 and Akt2 isoforms in HR." (PMID 31847370, 2019). "To analyze AKT isoform-specific expression and activation, we first characterized AKT specific antibodies using a set of parental and AKT knockout HCT116 colon cancer cells (AKT1−/−, AKT2−/−, and AKT1/AKT2 DKO)." (PMID 30012111, 2018). "Taken together, our results present strong support for the role of both AKT1 and AKT2 isoforms in the response to ionizing radiation and their interaction with DNA-PKcs and MRE11 in colon cancer cells." (PMID 24338765, 2014). "Stable knockdown of Akt2 in the IGF1R-dependent and highly metastatic colon cancer cell line GEO was performed to give a better understanding of the mechanism of cell death mediated by loss of pEzrin." (PMID 24581231, 2014).
colon carcinoma (continued). "We have further verified this interaction, with flow cytometry, western blot and mRNA expression analysis in the colon cancer cell-line DLD-1 by showing that knock-out of AKT1, AKT2 or both AKT1 and AKT2 increased the expression of CD44." (PMID 24760019, 2014). "Resveratrol is considered to be a promising anticancer drug for chemoprevention or therapy for colon cancer, targeting numerous cellular molecules, such as AKT serine/threonine kinase 1 (AKT1), AKT2, and AKT/GSK-3β/Snail signaling pathway, and increasing ROS production." (PMID 32244860, 2020). "We then raised the question whether AKT2 and E-cadherin expression are related in human CRC and evaluated immunoexpression of these genes in two sets of colon tumor tissue microarray containing tissue sections from the same cores." (PMID 26434583, 2016). "We have also analyzed the radiation sensitivity of the colon cancer cells sorted for CD133high/CD44high and CD133low/CD44low expression, and further investigated the influence of two AKT isoforms (AKT1, AKT2) on CD133 and CD44 expression, including CD44 splice variant isoforms." (PMID 24760019, 2014). "The CD133 expression was reduced in the AKT1 KO but not AKT2 KO colon cancer cell line, whereas the expression of CD44 was increased by both AKT1 KO and AKT2 KO." (PMID 24760019, 2014).
Obesity (27 papers, 2013 to 2025). Accumulation of substantial excess body fat. "In turn, the downregulation of miR-184 has been associated with obesity-related inflammation, insulin secretion, and resistance through aberrant PKCβ and AKT2 signalling." (PMID 41356094, 2025). "The interesting novel results suggest that Akt2 and Sirt1 may be implicated in porcine obesity." (PMID 23951196, 2013). "Our findings strongly demonstrate that siglec-E plays an adaptative role in protecting the adipocytes from inflammatory-mediated injury through reduced immune cell recruitment and TRAF3/Akt2 activity in AT during the early phase of obesity progression." (PMID 39967660, 2025). "Our findings are strikingly similar to the observation that the overexpression of the AKT1 isoform increased muscle fiber size and reduced dietary-induced obesity, albeit our increases in AKT2 were more robust than the increases in AKT1." (PMID 39408607, 2024). "Accordingly, we found that genes related to angiogenesis (e.g., ANGPT1, ANXA2), as well as to TGFβ signaling (e.g., SMAD4, BMPER, AKT2) are modulated in obesity condition." (PMID 30838002, 2019). "At 4 weeks, PIK3CB and AKT2 mRNA expression was higher by 47% and 23% respectively in perirenal adipose tissue of male offspring exposed to maternal obesity during pregnancy compared to offspring exposed to a control diet (P < 0.05)." (PMID 31300679, 2019). "Both patients studied here had normal liver triglyceride content, normal or low plasma triglyceride concentrations, and normal rates of fasting de novo lipogenesis despite low-level constitutive activation of AKT2 and obesity." (PMID 28541532, 2017). "Interestingly, mice with deletions of Akt2 and AMPKα2 exhibited effects that were protective against diet-induced obesity." (PMID 39967660, 2025). "Hence, it is plausible that mechanisms whereby Akt2 causes the activation of Rac1 are not affected by obesity." (PMID 37511290, 2023). "Akt2 and Sirt1 therefore may be involved in formation of porcine obesity." (PMID 23951196, 2013). "Taken together, these findings suggest that siglec-E plays a crucial role in obesity-induced inflammation by controlling the expression of TRAF3 and Akt2 in the AT." (PMID 39967660, 2025). "Insulin-stimulated phosphorylations of INSR, IRS-1, Akt2, and GSK3β were markedly reduced in the liver of HFD-fed mice, indicating that HFD-induced obesity impaired hepatic insulin signaling." (PMID 35328400, 2022). "In adult obesity models such as high fat diet (HFD), adipocyte precursors have been shown to require activation through the phosphoinositide 3-kinase (P13K)-AKT2 pathway in order to differentiate into mature adipocytes." (PMID 33679601, 2020). "For example, we observed that deletion of Akt1, but not Akt2, significantly blocked DJ-1 transgene-induced glucose intolerance and obesity." (PMID 28224045, 2017). "Although not significant, there was a trend of reduced AKT2 mRNA expression in 4-week-old offspring (P = 0.056), and reduced IRS2 mRNA expression in 12-week-old offspring (P = 0.052), which was associated with maternal obesity exposure during lactation." (PMID 31300679, 2019). "It is plausible that the activity of Rac1 is regulated downstream of AMPK by mechanisms other than those in insulin signaling involving Akt2, and therefore, Rac1 activation downstream of AMPK may not be impaired by obesity." (PMID 37511290, 2023).
Hyperglycemia (26 papers, 2013 to 2025). An increased concentration of glucose in the blood. "The marked hyperglycaemia and loss of pancreatic β cells and adipose tissue in Akt2-deficient mice suggest that AKT plays critical roles in glucose metabolism and the development or maintenance of proper adipose tissue and islet mass." (PMID 36837811, 2023). "M2698 has the potential to block the AKT compensatory feedback loop while avoiding the adverse effects of pan-AKT inhibition, including those associated with AKT2 inhibition (e.g., hyperglycemia)." (PMID 34407844, 2021). "Mice deficient in Akt2 develop hyperglycemia and hyperinsulinemia and are impaired in their ability to lower blood glucose in response to insulin." (PMID 24722238, 2014). "Similarly, mice deficient in AKT2 exhibited hyperglycemia and IR, underscoring AKT2’s crucial role in metabolic control." (PMID 41294822, 2025). "Akt2 knockout mice exhibited a diabetic phenotype accompanied by hyperglycemia, impaired INS action, reduced circulating leptin, and mild growth retardation, whereas Akt2 and Akt3 double knockout mice exhibited hyperinsulinemia, hyperglycemia, and reduced brain volume." (PMID 39984861, 2025). "Interestingly, adipocyte-specific deletion of AKT2 is sufficient to recapitulate severe lipodystrophy, liver steatosis and hyperglycemia and hyperinsulinemia despite normal glucose tolerance." (PMID 35250856, 2022). "First, pan-AKT and PI3K inhibitors are known to induce hyperglycemia, which is attributed to AKT2 inhibition; by sparing inhibition of AKT2, M2698 may have a more favorable and manageable safety profile." (PMID 34407844, 2021). "Akt2 knockout impaired glucose uptake in isolated soleus and extensor digitorum longus muscles on exposure to a low concentration of insulin, and Akt2 knockout mice indeed exhibited hyperglycemia and glucose intolerance." (PMID 30735546, 2019). "Akt2 null mice are known to develop mild hyperglycemia and hyperinsulinemia." (PMID 26654940, 2016). "However, in refed conditions, AT deletion of AKT2 leads to hyperglycemia." (PMID 35250856, 2022). "Inactivation of liver PI3K, AKT1, or AKT2 could induce hyperglycemia and hyperinsulinemia." (PMID 32280711, 2020). "Hyperglycaemia and insulin sensitivity via activation of AKT2 and AMPK were ameliorated, and the expression of GLUT4, AKT2, and AMPK, whose levels were reduced under diabetic conditions, increased." (PMID 39861420, 2025). "Catechins and quercetin, present in Amaranthus, improved hyperglycemia and insulin sensitivity through the activation of AKT2 and AMPK, increasing the expression of GLUT4, AKT2, and AMPK alpha 2, whose levels are reduced under diabetic conditions." (PMID 39434897, 2024). "Since canagliflozin was shown to inhibit hyperglycemia and hyperinsulinemia without adverse consequences, cotreatment with Akt or PI3K inhibitors that inhibit Akt2 in insulin-responsive tissues should be considered." (PMID 35578699, 2021). "Our previous study, which used NCD‐fed rats, showed that food restriction by pair‐feeding to E2 replacement group in the PL group ameliorated hyperglycemia in the OVX rats but failed to mimic the effects of E2 replacement on basal levels of insulin signaling components, Akt2 and AS160." (PMID 35238495, 2022).